E2F1 (E2F transcription factor 1)
Diseases named in the same sentence as E2F1 in open-access papers (continued):
Sharing a sentence is not in itself a finding about the gene and the disease.
pancreatic cancer (continued). "ZNF655 facilitated malignant behaviors of pancreatic cancer cells via promoting the binding of E2F1 to CDK1 promoter, which may contribute to the development of promising targets for tumor diagnosis and treatment." (PMID 35927248, 2022). "Additionally, gemcitabine also promotes the expression of the ribonucleotide reductase M2 (RRM2) subunit in pancreatic cancer cells through the ERK/E2F1 pathway, promoting deoxyribonucleotide biosynthesis and inhibiting gemcitabine-induced DNA damage." (PMID 32122374, 2020). "Our results point at E2F1 as a regulatory factor modulating gemcitabine induced VMP1-mediated autophagy in human pancreatic cancer cells and mechanistically integrate the autophagic degradative process into the complex network of events involved in PDAC chemoresistance." (PMID 32655498, 2020). "Besides, we demonstrated a direct binding of E2F1 on VMP1 promoter under gemcitabine treatment in pancreatic tumor cells." (PMID 32655498, 2020). "Besides, pancreatic tumor cells transfected with an expression vector for E2F1 induced VMP1 expression and activated autophagy." (PMID 32655498, 2020). "Studies in pancreatic cancer show that inhibition of E2F1 expression could minimize gemcitabine resistance." (PMID 28797284, 2017). "However, the role of E2F1 in tumors, such as those of gastric and pancreatic cancers is still debatable." (PMID 28797284, 2017). "Arginine deprivation in pancreatic cancer cells auxotrophic for arginine appears to have multiple effects though we propose the primary mechanism in the chemosensitizing effect in combination with gemcitabine is through E2F-1-mediated regulation of RRM2 following gemcitabine exposure." (PMID 25499121, 2014). "Additionally, previous studies have identified E2F1 as a critical factor in regulating tumor stem cell characteristics and signaling pathways, playing a central role in chemotherapy resistance and mediating autophagy induced by gemcitabine in pancreatic cancer cells." (PMID 40886002, 2025). "Silencing of E2F1 and E2F8 in PANC‐1 pancreatic tumor cells inhibited cell proliferation and impaired cell spreading and migration." (PMID 38686617, 2024). "E2F1 and E2F8 mainly positively correlate with the same genes in PDAC tissues, suggesting similar and redundant functions, as observed experimentally in pancreatic cancer cells." (PMID 38686617, 2024). "Mechanistically, experiments performed in pancreatic cancer cell lines have shown that gemcitabine treatment induces VMP1 expression through a pathway involving the Transcription Factor E2F1 (E2F1), and EP300 ultimately triggering autophagy." (PMID 38612567, 2024). "COL6A3 functions in tumorigenesis and progression of cholangiocarcinoma through the E2F1/LMCD1-AS1/miR-345-5p/COL6A3 axis and serves as prognostic factor for pancreatic cancer." (PMID 35036081, 2022). "Our experimental findings point at E2F1 and VMP1 as novel potential therapeutic targets in precise treatment strategies for pancreatic cancer." (PMID 32655498, 2020). "In this paper, we investigated the role of E2F1 and STAT1 transcription factors on MUC4 regulation in pancreatic cancer cells and found that both the transcription factors can positively regulate MUC4 transcription." (PMID 22537161, 2012). "Our studies show that agents that can promote the growth and invasion of pancreatic cancer cells induce the MUC4 gene through multiple pathways and this induction requires the transcriptional activity of E2F1 and STAT1." (PMID 22537161, 2012). "We find a positive correlation between the binding of E2F1 and STAT1 with MUC4 promoter and its expression in pancreatic cancer cell lines." (PMID 22537161, 2012). "We observed that oncogenes intersecting with the RB pathway and known as cell-autonomous inducers of G1/S transition (e.g. E2F1, E2F4), supported proliferation, chemoresistance and cell migration of pancreatic cancer cells via inducing the secretion of canonical WNT signalling." (PMID 38678032, 2024).
pancreatic cancer (continued). "As a key downstream gene of KAT2A and E2F1, we also found that UBE2C significantly inhibited the proliferation of the liver cancer cell line, HepG2, and pancreatic cancer cell line, BxPC3, through a CCK-8 assay, which suggested that UBE2C plays a critical role in pan-cancer." (PMID 36292703, 2022). "To determine protein levels of the mRNAs modulated by DHA via microRNAs, we next examined Cdk4, Cdk6, VEGF, IKKα, MEK1, E2F3, Rac1, E2F1, and CDC42 protein levels, which affect growth, inhibit angiogenesis, and promote apoptosis in DHA-treated and vehicle-treated pancreatic cancer cells." (PMID 27613829, 2016). "Surprisingly, we found that four crucial microRNAs (miR-34a-5p, miR-195-5p, miR-30c-5p, and miR-130b-3p) regulated the expression of many mRNAs (Cdk4, Cdk6, VEGF, IKKα, MEK1, E2F3, Rac1, E2F1, ERK1, and CDC42) and their proteins, and thus were crucial to the anti-pancreatic cancer effects of DHA." (PMID 27613829, 2016). "Given that nicotine stimulates the binding of E2F1 to a variety of promoters, and since STAT1 is known to induce MUC4, we decided to examine whether these factors mediate the induction of MUC4 in pancreatic cancer cells." (PMID 22537161, 2012). "Mechanistically, E2F Transcription Factor 1 (E2F1) may bind to the promoter of PNO1 to promote the transcriptional expression of PNO1, thus inhibiting ferroptosis and promoting the malignant progression of pancreatic cancer." (PMID 39769097, 2024). "E2F1, which was preferentially essential in pancreatic cancer cells, has been previously shown to regulate both pancreatic B-cell development and cancer growth by increasing the expression of PDK1 and PDK3 which results in increased aerobic glycolysis and growth in pancreatic cancers." (PMID 36727483, 2023). "Increased thymidylate synthase expression in gemcitabine-treated pancreatic cancer cells might also adopt the same E2F1-dependent pathway, but this effect is not very clear yet." (PMID 32122374, 2020).
non-small cell lung carcinoma (43 papers, 2009 to 2025). A group of at least three distinct histological types of lung cancer, including non-small cell squamous cell carcinoma, adenocarcinoma, and large cell carcinoma. "E2F1 overexpression acts as a growth-promoting factor and is associated with poor prognosis in non-small cell lung cancer." (PMID 33613291, 2021). "The knockdown of ABH4 suppressed transcription factor E2F1 and expression of its target gene in non-small cell lung cancer cells." (PMID 39329974, 2024). "Expression levels of ABH4 and E2F1 significantly correlated in clinical samples of non-small cell lung cancer." (PMID 39329974, 2024). "It was demonstrated that E2F1 regulated the transcriptional levels of target genes depending on the ERK1/2 pathway in advanced non-small cell lung cancer (NSCLC)." (PMID 37128280, 2023). "LINC00847 induces by E2F1 facilitates non-small cell lung cancer progression by targeting the miR-147a/IFITM1 axis." (PMID 36864364, 2023). "Overall, this work unveiled a new regulatory mechanism that, by increasing E2F1 protein, modifies the non-small cell lung cancer cells transcriptional program, leading to enhanced aggressiveness features." (PMID 37980331, 2023). "For example, E2F1 transcriptional activation of neural epidermal growth factor-like 2 (NELL2) accelerates the progression of non-small cell lung cancer." (PMID 36249071, 2022). "FOXM1 acts as a target gene of E2F1, mediating the non-small cell lung cancer (NSCLC) proliferation initiated by the lncRNA-HIT–E2F1-FOXM1 axis." (PMID 30992007, 2019). "Though E2F1 played a tumour-suppressing role in CRC, its expression was usually increased in non-small cell lung cancer and associated with worse patient prognosis." (PMID 26704889, 2015). "It has been reported that GCN5 can promote cell proliferation through enhancing E2F1 in non-small cell lung cancer." (PMID 26378521, 2015). "The over-expression of e2f-1 in non-small cell lung cancer can activate the expressions of thymidylate synthase and survivin, and then encourage the proliferation of tumors, finally resulting in the worse prognosis." (PMID 24393368, 2014). "miR-26a could regulate the resistance of human non-small cell lung cancer to cisplatin by regulating the expression of HMGA2 through the E2F1-Akt pathway." (PMID 34856955, 2021). "Conversely, non-small cell lung cancer expresses lower levels of E2F-1 and higher levels of Hes-1, indicating that Hes factors may be important in E2F-1 regulation in these cancers as well." (PMID 19891787, 2009). "In non-small-cell lung cancer (NSCLC), SNHG3 activation by E2F1 drives proliferation and migration via the TGF-β and IL-6/JAK2/STAT3 pathways, underscoring its therapeutic relevance." (PMID 39349640, 2024). "In non-small cell lung cancer, SUZ12 promotes cell proliferation and metastasis by decreasing E2F transcription factor 1 (E2F1) gene expression." (PMID 35563864, 2022). "In non-small cell lung cancer, ANKRD22 up-regulated the transcription of E2F1 and promoted the progression of cancer cells by enhancing cell proliferation." (PMID 34584137, 2021). "In non-small cell lung cancer (NSCLC), GCN5 enhances cell proliferation and G1/S transition by regulating the expression of cell cycle proteins like cyclin D1, E1 and E2F1." (PMID 27322556, 2016). "We found that the miR-17 family exerted important effects in the regulation of non-small cell lung cancer, such as in proliferation and cell cycle regulation by targeting the retinoblastoma protein (RB1) and forming a feed forward loop with the E2F1 TF." (PMID 24200043, 2013). "We proposed a model for the miR-17 family, E2F1, and RB1 to demonstrate their potential roles in the occurrence and development of non-small cell lung cancer." (PMID 24200043, 2013).
non-small cell lung carcinoma (continued). "E2F1, E2F2, and E2F3 are up-regulated in non-small cell lung cancer." (PMID 29254182, 2017). "In non-small cell lung cancer, miR-342-3p has been suggested to play a tumor-suppressive role by negatively regulating RAP2B (a member of the RAS oncogene family) and MYC transcriptional activity by targeting E2F1 (a MYC-cooperating molecule)." (PMID 28035073, 2017). "Nevertheless, a recent publication demonstrated that E2F1 could recruit to SCF promoter and induce SCF expression in non-small cell lung cancer cells." (PMID 26704889, 2015). "Knock-down of E2F1 and E2F3 inhibited migration and invasion of non-small cell lung cancer cells." (PMID 25568667, 2014).
glioblastoma (41 papers, 2009 to 2025). The most malignant astrocytic tumor (WHO grade IV). "Given that E2F1 dysregulation has been associated with the progression of glioblastomas, E2F1 as a target to improve the BBB and cognitive functions has to be considered very cautiously." (PMID 40761766, 2025). "Another study in glioblastoma showed that BRCA1 regulates RRM2 expression via E2F1, and RRM2 inhibition mimics the phenotype of BRCA1-loss in glioblastoma cells." (PMID 38124207, 2023). "In the brain, E2F1 has been mostly implicated in the progression of glioblastoma." (PMID 40761766, 2025). "And E-NPP1-deficient glioblastoma CSCs led to a decrease in the transcriptional function of E2F1, and classical E2F1 target genes facilitating G1/S transition were downregulated, resulting in the accumulation of cells in G1 phase and inhibition of their proliferation." (PMID 34476219, 2021). "The early 2-factor (E2F) family of transcription factors, including E2F1 through 8, plays a critical role in apoptosis, metabolism, proliferation, and angiogenesis within glioblastoma (GBM)." (PMID 39061176, 2024). "As a well-known oncogene, E2F-1 is widely reported to be highly expressed in various cancers, including glioblastoma." (PMID 38017538, 2023). "Using bioinformatics methods, we discovered a positive correlation between MAD2L2 and E2F-1 expression in multiple publicly available glioblastoma datasets." (PMID 38017538, 2023). "MiR-302-367 cell-to-cell transfer decreases the expression levels of CXCR4/SDF1, SHH, cyclin D, cyclin A, and E2F1 to inhibit glioblastoma growth." (PMID 34113619, 2021). "E2F1 has been reported to facilitate glioblastoma development, where it accelerates cell growth under CDDP treatment." (PMID 34726120, 2021). "Taken together, our study revealed that repressed cell growth and elevated cell apoptosis of glioblastoma cells occurred via the miR-485-5p-E2F1 axis under CDDP treatment." (PMID 34726120, 2021). "Collectively, the data indicate that CDDP hampers cell growth and promotes cell apoptosis via the miR-485-5p-E2F1 axis in glioblastoma." (PMID 34726120, 2021). "Although our study has revealed that miR-485-5p inhibits glioblastoma cell progression under CDDP treatment by targeting E2F1, the specific signaling pathways require further exploration." (PMID 34726120, 2021). "We identified miR-485-5p downregulation and E2F1 upregulation in glioblastoma, and miR-485-5p inhibited cell growth and elevated cell apoptosis in glioblastoma cells after CDDP treatment." (PMID 34726120, 2021). "Meanwhile, animal models should be applied to confirm the role of the CDDP-miR-485-5p-E2F1 axis in glioblastoma." (PMID 34726120, 2021). "In glioblastoma CSCs, the bromodomain inhibitor JQ1 was found to cause cell cycle arrest and suppress CSC proliferation by preventing the release of E2F1 from the RB/E2F1 complex." (PMID 34476219, 2021). "The expression of miR-485-5p and E2F1 was investigated by quantitative real-time polymerase chain reaction or western blotting in glioblastoma tissues and cell lines." (PMID 34726120, 2021). "Consistent with this study, we demonstrated that E2F1 overexpression promoted glioblastoma cell proliferation, adhesion, and migration, and retarded cell apoptosis with CDDP treatment." (PMID 34726120, 2021). "Recent studies show that lncRNAs and miRNAs function in an antagonistic fashion to regulate E2F1 expression, ultimately affecting cell proliferation, glioblastoma growth, and response to therapy." (PMID 32488114, 2020). "Specifically, we found that three E2F members showed decreased expression upon radiation: E2F1, E2F2, and E2F8, all of which have been previously implicated in glioblastoma development." (PMID 32488114, 2020). "In the case of MYBL2, this may be due to EGFR signaling, which is frequently amplified and overexpressed in IDH-wildtype glioblastomas and was reported to activate the MYBL2 promoter in association with E2F1." (PMID 35228525, 2022).
glioblastoma (continued). "This study revealed miR-485-5p downregulation and E2F1 upregulation in glioblastoma tissues." (PMID 34726120, 2021). "Moreover, miR-485-5p targeting E2F1 repressed cell growth and improved cell apoptosis in glioblastoma cells after CDDP treatment." (PMID 34726120, 2021). "Our study is the first to show that the CDDP-miR-485-5p-E2F1 axis plays a key role in glioblastoma." (PMID 34726120, 2021). "Therefore, we aimed to investigate the effect of the miR-485-5p-E2F1 axis in glioblastoma cells under CDDP treatment." (PMID 34726120, 2021). "In this study, we hypothesized that miR-485-5p inhibits glioblastoma progression by suppressing E2F1 expression under CDDP treatment." (PMID 34726120, 2021). "Nonetheless, whether CDDP affects glioblastoma progression via the miR-485-5p-E2F1 axis requires investigation." (PMID 34726120, 2021). "miR-485-5p and E2F transcription factor 1 (E2F1) dysfunction has been reported in glioblastoma." (PMID 34726120, 2021). "It was hypothesized that CDDP-assisted miR-485-5p might reduce E2F1 expression following CDDP treatment in glioblastoma." (PMID 34726120, 2021). "Our study revealed that CDDP retarded glioblastoma cell development via the miR-485-5p-E2F1 axis, which may be a new direction for glioblastoma therapy." (PMID 34726120, 2021). "Seven candidates were identified to target E2F1 and be downregulated in glioblastoma samples." (PMID 34726120, 2021). "In a recent study to evaluate early changes in expression in glioblastoma cells after radiation, we determined that down-regulation of genes implicated in the cell cycle, DNA repair and DNA replication is likely the result of decreased expression of FOXM1, E2F1, E2F2 and E2F8." (PMID 33804958, 2021). "Moreover, miR-485-5p targeting E2F1 repressed glioblastoma progression following CDDP treatment." (PMID 34726120, 2021). "Importantly, miR-485-5p could repress E2F1 expression and suppressed glioblastoma cell development under CDDP treatment." (PMID 34726120, 2021). "Notably, the function of the miR-485-5p-E2F1 axis in glioblastoma with CDDP treatment is unclear." (PMID 34726120, 2021). "It was revealed that the CDDP-miR-485-5p-E2F1 axis may be a new direction for glioblastoma therapy." (PMID 34726120, 2021). "To determine whether bpV[pic]-induced neuroprotection in ICH is mediated through E2F1 and β-catenin signaling, we examined the expression of E2F1 and β-catenin in primary cortical neurons and the PTEN-deficient human glioblastoma U251 cells after treatment with bpV[pic] or PTEN siRNA." (PMID 31866820, 2019). "Each of these transcription factors harbors oncogenic or tumor-promoting functions and some of them were reported to be overexpressed in cancer, including overexpression of E2F1, E2F6, FOXM1, and MYBL2 in glioblastomas." (PMID 35228525, 2022). "miR-1258 arrested the cell cycle in G0/G1 phase by targeting E2F1 and E2F8 in CRC, BC, CC, and glioblastoma." (PMID 36249037, 2022). "Thus, the CDDP-miR-485-5p-E2F1 axis may be an innovative direction for glioblastoma therapy." (PMID 34726120, 2021). "Previous studies exhibited that, in glioblastoma, there was an EZH2-CDK4/6-pRb-E2F1 signal loop that mediated cell cycle and cellular proliferation." (PMID 33330073, 2020). "In research on glioblastoma, a correlation between the expression of E2F1 and hTERT was found; patients with a low level of E2F-1 expression had a much better prognosis." (PMID 22649586, 2009). "In light of these observations, the existing mechanical relationship between the activation of the LPR6/GSK3/E2F1 axis and LSH expression in glioblastoma could be interpreted as a key role in GBM." (PMID 36146527, 2022).